CSF3 (colony stimulating factor 3)
Description:
Granulocyte/macrophage colony-stimulating factors are cytokines that act in hematopoiesis by controlling the production, differentiation, and function of 2 related white cell populations of the blood, the granulocytes and the monocytes-macrophages. This CSF induces granulocytes.
Synonyms: C17orf33; GCSF; MGC45931; CSF3OS; formerly G-CSF
Tractability: Small molecule: it has a high-quality binding pocket. Antibody: its Gene Ontology location is reachable by antibodies, with high confidence; UniProt places it where antibodies can reach, with medium confidence; UniProt predicts a signal peptide or a membrane-spanning region.
Gene: Protein-coding gene on chromosome 17 (40,015,361 to 40,017,816, forward strand). Ensembl gene ENSG00000108342.
Subcellular location: Secreted
Pathways (Reactome):
Immune System: Inactivation of CSF3 (G-CSF) signaling; Interleukin-10 signaling; Other interleukin signaling; Signaling by CSF3 (G-CSF)
Gene Ontology:
Molecular function: cytokine activity; enzyme binding; granulocyte colony-stimulating factor receptor binding; growth factor activity
Biological process: cellular response to cytokine stimulus; granulocyte colony-stimulating factor signaling pathway; positive regulation of actin filament polymerization; positive regulation of phosphatidylinositol 3-kinase/protein kinase B signal transduction; positive regulation of transcription by RNA polymerase II; regulation of actin filament organization; cytokine-mediated signaling pathway; granulocyte differentiation; macrophage differentiation; positive regulation of cell population proliferation; positive regulation of myeloid cell differentiation; cellular response to lipopolysaccharide; immune response; response to ethanol
Cellular component: endocytic vesicle lumen; extracellular region; lysosomal lumen
Genetic constraint (gnomAD): Loss-of-function variants: 18 observed, 21.58 expected, observed/expected ratio (o/e) 0.83, 90% interval 0.58 to 1.24. The upper end of that interval is the gene's LOEUF score, 1.24, which puts it in group 5 of 6, group 1 being the genes least tolerant of losing a copy. Missense variants: 210 observed, 250.49 expected, observed/expected ratio (o/e) 0.84, 90% interval 0.75 to 0.94. Synonymous variants: 125 observed, 109.24 expected, observed/expected ratio (o/e) 1.14, 90% interval 0.99 to 1.33.
Homologues: Orthologues: chimpanzee CSF3 (99% identical), macaque CSF3 (94% identical), dog CSF3 (81% identical), pig CSF3 (79% identical), rabbit CSF3 (79% identical), rat Csf3 (74% identical), mouse Csf3 (74% identical), guinea pig CSF3 (66% identical), tropical clawed frog csf3 (26% identical), zebrafish csf3b (19% identical), zebrafish csf3a (19% identical).
Diseases named in the same sentence as CSF3 in open-access papers:
CSF3 is named in the same sentence as 807 diseases in open-access papers, as found by Europe PMC text mining. Sharing a sentence is not in itself a finding about the gene and the disease. The quoted sentences say what the papers report.
neutropenia (1,186 papers, 1995 to 2026). A decrease in the number of neutrophils found in the blood. "Several genes exemplified this scenario such as IL36G and IL36RN associated with psoriasis, and CSF3 associated with severe neutropenia." (PMID 40208878, 2025). "Granulocyte-macrophage colony-stimulating factor (CSF) (also known as CSF2) and granulocyte-CSF (also known as CSF3, G-CSF) are important survival and proliferation factors for neutrophils and macrophages, and deficiency of CSF3 leads to neutropenia." (PMID 38745657, 2024). "This is interesting given the disease association of this locus with RA and asthma, and the clinical utility of granulocyte colony stimulating factor (encoded by CSF3) in treating neutropenia." (PMID 23122694, 2013). "Additionally, although CSF3 has been applied as a supportive therapy to prevent or treat chemotherapy-associated neutropenia in cancer patients, emerging investigations have drawn attention to the tumor-promoting effects of CSF3 on myeloid cells." (PMID 38167409, 2024). "The major adverse events were radiation oesophagitis (grades I–II and III–IV), decreased neutrophil counts and fatigue, and neutropenia was managed with CSF3." (PMID 39507704, 2024). "Granulocyte colony-stimulating factor (G-CSF) or colony-stimulating factor 3 (CSF3) is widely used for the clinical treatment of patients with neutropenia after chemotherapy, radiotherapy, or hematopoietic stem cell transplantation." (PMID 34248610, 2021). "Severe congenital neutropenia (SCN) patients treated with CSF3/G-CSF to alleviate neutropenia frequently develop acute myeloid leukemia (AML)." (PMID 33205068, 2020). "CSF3 treatment is a successful therapy to alleviate neutropenia in the majority of these patients but does not cure the disease nor does it prevent malignant transformation." (PMID 34854832, 2022). "Similarly, direct overexpression of colony stimulating factor 3a (Csf3a/G-CSF), a haemopoietic growth factor relatively specific for neutrophils, resulted in vigorous neutrophil expansion in WT but failed to rescue the neutropenia of mne." (PMID 28382966, 2017).
COVID-19 (392 papers, 2020 to 2025). A disease caused by infection with severe acute respiratory syndrome coronavirus 2. "Hyperinflammation in COVID-19 is associated with such an elevation of proinflammatory cytokines, interleukins, and tumor necrosis factor-α (TNF) and a large number of TNF-induced proteins, and granulocyte colony stimulating factor (GCSF or CSF3)." (PMID 32545518, 2020). "Previous studies reported that COVID-19 is frequently associated with a massive production of 14 cytokines including IFN-γ, IL-1RA (IL1RN), IL-2RA, IL-6, IL-10, IL-18, HGF, MCP-3 (CCL7), MIG (CXCL9), M-CSF (CSF1), G-CSF (CSF3), MIG-1a (CCL3), CTACK (CCL27), and IP-10 (CXCL10)." (PMID 34262555, 2021). "Therefore, we have screened drugs that may potentially target CSF3 for the treatment of COVID-19 from the FDA-approved drug library." (PMID 33551833, 2020). "We regarded CSF3 as a potential drug target, and used molecular docking and virtual drug screening technology to find drugs that may interact with it to find potential treatments for COVID-19." (PMID 33551833, 2020). "It has been proposed that CSF can be used as an early warning marker of whether COVID-19 causes myocardial injury, or to treat COVID-19 by interfering with the CSF pathway, but neither CSF nor CSF3 was found in the results of our analysis of human single-cell data." (PMID 38745657, 2024). "In the COVID-19 cohort, IL6, PTSG2, JUN, ATF3, SOCS3, CSF3, and NFKB2 had AUC values greater than 0.7." (PMID 36380355, 2022). "Our study also found 4 additional targets (CCL20, CSF3, CXCL1, CXCL10) with existing therapies that have yet to be trialed in the COVID-19 patient population." (PMID 34582497, 2021). "Subsequently, Paxlovid was analyzed against the core targets of LUAD/COVID-19 (CXCL2, CCL2, IL12B, CSF3, LBP, IL6, CXCL10) and Paxlovid, and the results showed that IL-6, IL12B, LBP and Paxlovid could be combined." (PMID 36157452, 2022). "We additionally found 4 potential targets (CCL20, CSF3, CXCL1, CXCL10) with 6 existing drugs that could be repurposed for the treatment of COVID-19." (PMID 34582497, 2021). "Transcriptomic studies revealed remarkably enhanced expressions of CCL2, CXCL8, CSF3, CSF2, and CXCL10 in Calu-3 cells infected with SARS-CoV-2, inflammatory factors that were shown to be strongly elevated in the serum of patients with severe clinical symptoms of COVID-19." (PMID 34578229, 2021). "Also, we found 6 existing drugs against 4 potential anti-COVID-19 targets (CCL20, CSF3, CXCL1, CXCL10) that might have novel anti-COVID-19 indications." (PMID 34582497, 2021). "Importantly, our meta-analysis identified 4 potential novel targets (CCL20, CSF3, CXCL1, CXCL10) associated with COVID-19 pathogenesis, targeted by 6 existing drugs that have not been studied in clinical trials for treatment of COVID-19 and could be repurposed." (PMID 34582497, 2021).
breast cancer (268 papers, 1994 to 2026). A primary or metastatic malignant neoplasm involving the breast. "Nevertheless, CSF3 is strongly upregulated in a breast cancer cell line with high potential for lymph node metastasis." (PMID 36982170, 2023). "For example, CSF3 (AKA granulocyte colony-stimulating factor, G-CSF) has been shown to act through multiple mechanisms to enhance breast cancer metastasis." (PMID 35614362, 2022). "Consistent with observations for Csf3 KD mammary cancer cells, pharmacological inhibition of G-CSFR alleviated vessel remodelling in macroscopic bone lesions and offered modest protection against tumour-induced bone degradation." (PMID 34836954, 2021). "Most importantly, the overexpression of Csf3 in EMT6.5 mammary tumour cells or ablation of Csf3 in 4T1.2 cells was found to promote or diminish BM vessel remodelling, respectively." (PMID 34836954, 2021). "Moreover, orthotopic mammary tumor xenografts of either TuBo-p140Cap or 4T1-140Cap cells revealed lower Csf3 mRNA levels compared to tumors of equivalent size generated by their respective mock counterparts." (PMID 37169737, 2023). "We selected the top two downregulated cytokines from the RNA-seq data, namely granulocyte colony-stimulating factor (G-CSF or CSF3) and interleukin-6 (IL-6), both of which have been reported to support breast cancer growth in various ways, and confirmed their downregulation by RT-qPCR." (PMID 38250802, 2023). "CSF3 administration alongside chemotherapy has been shown to increase the risk of tumor regrowth in a model of breast cancer, although the same effect was not seen in a lung cancer mode." (PMID 33606788, 2021). "RNA sequencing analysis further revealed that phosphoglucomutase 2-like 1 (PGM2L1) is a downstream target of the CSF3/CSF3R signaling, enhancing the glycolysis pathway and providing energy to support the malignant phenotype of breast cancer." (PMID 40185722, 2025). "Surprisingly, compared to ob-aT bASCs, ln-aT bASCs are less efficient in stimulating the proliferation of epithelial-like breast cancer cell lines BT474, MCF7 and MDA-MB-361, defying their secretion of cytokines such as FGF/FGF2, CSF3, CXCL10 and LIF." (PMID 36710348, 2023). "Among these different CAF subtypes, iCAFs are reported to have a particular effect on chemoresistance in breast cancer patients, probably due to their high secretion of cytokines involved in therapy resistance, such as CXCL1–3, CCL2, CSF3, CXCL10, IL1β and LIF." (PMID 36710348, 2023). "To evaluate whether tumour cell-intrinsic G-CSF production drives vessel remodelling, we expressed Csf3 in EMT6.5 mammary tumour cells." (PMID 34836954, 2021).
Sepsis (214 papers, 2004 to 2026). Sepsis is defined as life-threatening organ dysfunction caused by a dysregulated host response to infection. "S100A8, MMP8, CSF3 and IL-6 protein levels in the peripheral blood of sepsis patients were revealed to be substantially associated with GCS scores following a correlation investigation of the four extracellular molecules with clinical indications (all p<0.05)." (PMID 37901226, 2023). "The fact that this CSF3 increases granulocytes and monocytes-macrophages and is closely linked to sepsis is undeniable." (PMID 37901226, 2023). "Firstly, XBJ effectively reversed lung injury caused by sepsis and restrained neutrophils recruitment to lung by down-regulating proinflammatory chemokines, such as CSF-3, CXCL-2, and CXCR-2." (PMID 36467039, 2022). "The concentrations of the proteins S100A8, MMP8, CSF3, and IL-6, were measured in peripheral blood samples from 31 sepsis patients to validate the critical extracellular proteins identified in the study." (PMID 37901226, 2023). "GeneWalk analysis identified potential regulatory genes involved in sepsis, including IL1B, CDKN1A, CDK2, CSF3, and IL1R2, which were included among the SRGs." (PMID 40303348, 2025). "Genes such as CSF3, ELANE, F5, and GALT exhibited significant differential expression between sepsis patients and controls." (PMID 41194984, 2025).
Stroke (112 papers, 2006 to 2025). Sudden impairment of blood flow to a part of the brain due to occlusion or rupture of an artery to the brain. "Notably, analysis of 341 DE mRNA associated with stroke (259 upregulated, 82 downregulated) in the IR group revealed upregulation of genes like Ccl2, Cxcl1, C3, Serpine1, Adamts7, Csf3, Ptx3, MMP8, Lif, and Lcn2, and downregulation of Gdf10, Agtr2 and Shank3." (PMID 39170713, 2024). "Csf3, as a proinflammatory cytokine, can pass through the blood-brain barrier (BBB) and plays a neuroprotective role in stroke." (PMID 34457033, 2021).
anemia (110 papers, 2002 to 2026). A reduction in the number of red blood cells, the amount of hemoglobin, and/or the volume of packed red blood cells. "Although more than 5% myeloblasts in the PB are a characteristic of AML, none of the CSF3-treated d715-RHD mice showed acute symptoms of AML, such as bleeding or anemia." (PMID 33205068, 2020).
multiple myeloma (102 papers, 1997 to 2025). "However, IL-6 and IL-6R antibodies can block CSF3-induced myeloma cell proliferation." (PMID 37250588, 2023). "CSF3 promoted the proliferation of myeloma cells, although it did not affect the expression of IL-6 and IL-6R, indicating that IL-6 does not mediate the proliferative effects of CSF3." (PMID 37250588, 2023).
acute myeloid leukemia (100 papers, 1987 to 2026). Acute myeloid leukemia (AML) is a group of neoplasms arising from precursor cells committed to the myeloid cell-line differentiation. "SCN patients are at risk of developing high-risk myelodysplastic syndrome (MDS) or acute myeloid leukemia (AML), with a reported median incidence of 21%, 15 years after initiation of CSF3 treatment." (PMID 33205068, 2020).
lung carcinoma (64 papers, 1999 to 2026). "Stromal fibroblasts release IL-6, CSF3, and Activin-A, which promote the dedifferentiation of lung carcinoma cells to cancer stem cells." (PMID 39338937, 2024). "In A549 (AT2; alveolar cell type II phenotype lung cancer cell), TGF-β1 treatment induced myofibroblast marker and CSF3 expression, but surfactant protein expression was reduced, which was restored by FB-101 treatment." (PMID 41034234, 2025). "Given the previous study in lung epithelial cells and lung cancer, as well as the results in this study, we speculated that miR-6515-5p might involved in the progression of PLF by modulating CSF3 expression." (PMID 40287741, 2025). "Interestingly, some incoming signaling pathways were found to be specific to one subtype of lung cancer, as exemplified by HGF (a new highlight in the treatments of lung cancer), KIT (activating the JAK/STAT and PLC/PKC signaling pathways) in LUAD, and the CSF3 and CDH5 in LUSC." (PMID 36008393, 2022).
colitis (51 papers, 2010 to 2026). Inflammation of the colon. "In addition, CSF3−/− mice are more susceptible to acute DSS-induced colitis than wild-type mice due to an impaired immune response." (PMID 35163326, 2022). "The expression of CSF3, an essential component of the intestinal response to prevent colitis and restore mucosal barrier integrity, was highly expressed in the C:15-treated mice." (PMID 39275347, 2024). "After 7 days of induced colitis, the gene expression of Osm and Csf3 was at the same level in all experimental groups, while the gene expression of Spp1 was still higher in CβG− and CβGl+ groups compared to the HβG− group." (PMID 35163326, 2022). "Moreover, two new essential factors were identified in reactive glia in POI, Csf1 and Csf3, with Csf1 recently implicated in EGC responses in a murine colitis model and human Crohn’s Disease28." (PMID 35962064, 2022). "TLR4 is a Toll-like receptor and has been reported to have a repairing effect on DSS-induced intestinal injury and up-regulation of IL6, CCL2 and CSF3, which may also be related to their therapeutic effects on TNBs-induced colitis." (PMID 35831878, 2022). "More importantly, mesalazine treatment reversed the suppressive effect of immune responsive genes, including chemokine (C–X–C motif) ligand (CXCL3), chemokine (C–C motif) ligand (CCL11 and CCL21), chemokine receptor (CXCR2), and colony-stimulating factor (CSF3) in the DSS-induced colitis model." (PMID 34456974, 2021). "In DSS colitis, increased levels of IL-6, CSF3, and IL-17 were further increased in Smox−/− mice." (PMID 29922289, 2018). "After 7 days of induced colitis, upregulation of the expression of 22 genes (Ccl2, Ccl3, Ccl4, Ccl5, Ccl6, Ccl7, Ccl12, Ccl17, Cxcl1, Cxcl2, Cxcl6, Cxcl9, Cxcl11, Ccr1, Ccr2, Ccr3, Ccr5, Ccr8, Cxcr2, Csf3, Osm, and Spp1) was observed in the CβG− group compared to the HβG- control group." (PMID 35163326, 2022). "While A2BR signaling mediates glial upregulation of Il6 and downregulation of Csf3, Cxcl1, and Cxcl10, glial A2BRs in colon tissue mediated the DSS colitis-induced increase in protein expression of all these mediators." (PMID 35869148, 2022). "The pro‐inflammatory cytokines IL1A, IL1B, IL6, and CSF3 and chemokines CXCL1 and CXCL2 were significantly increased, and the frequency of CD11b+Ly6G+ neutrophils was higher in CD11c‐Cre+Rab32f/f colitis mice." (PMID 30338217, 2018). "IL-6, CSF3, TNF-α, and IL-17 were also induced in the colon of DSS-treated WT mice compared to untreated animals; the levels of induction were comparable to those observed in C. rodentium colitis." (PMID 29922289, 2018).
congenital neutropenia (44 papers, 2008 to 2025). "CSF3R encodes the receptor for CSF3, a cytokine that controls the proliferation and differentiation of granulocytes, and is also mutated in a severe form of congenital neutropenia (MIM# 617014)." (PMID 28787443, 2017). "Similarly, in humans, single gene mutations have been described in both CSF3 and CSF3R resulting in severe congenital neutropenia (SCN)." (PMID 33236983, 2020).
viral infection (37 papers, 2011 to 2025). "TNFAIP3, ULBP1 and TIAM1 were consistently down-regulated by viral infection, while CCL8, CCL11, CXCL11, NCF2, CSF3 and PRKCB were significantly up-regulated after infection." (PMID 28938587, 2017). "Among the pro-inflammatory mediators, a significant increase in mRNA for CSF2, CSF3, CXCL2, CXCL5, IL6, IL8, and also IL1 and IL18 was observed 24 h after viral infection." (PMID 23723976, 2013). "Indeed, the knockdown of DUSP1 or the m6A eraser ALKBH5 enhanced the expression of innate immune response genes, including IL-1β, CSF3, TGM2, and SRC, during bacterial or viral infections." (PMID 36625590, 2023). "The expression of the csf3 gene in tadpole and adult intestines was not significantly altered by viral infections." (PMID 34489981, 2021).